HOXB13 (homeobox B13)
Diseases named in the same sentence as HOXB13 in open-access papers (continued):
Sharing a sentence is not in itself a finding about the gene and the disease.
prostate carcinoma (continued). "Functionally, HOXB13 plays oncogenic roles in promoting progression and castration resistance of prostate cancer." (PMID 36609444, 2023). "Nevertheless, some studies have reported that HOXB13 is downregulated in colorectal, kidney, and prostate cancers." (PMID 37627895, 2023). "Family history/genetics was widely accepted and an undisputed risk factor, with men with a family member with a history of breast cancer or those with gene (HOXB13) identified as more likely to develop prostate cancer." (PMID 37893854, 2023). "Mechanistically, SLC12A5 interacts with the m6A reader YTHDC1 in the nucleus and in turn upregulates the transcription factor HOXB13 to promote the tumor progression of prostate cancer." (PMID 36609444, 2023). "The authors suggested that the lncRNA HOXA11-AS, together with its transcription factor HOXB13, regulates the bone tropism of prostate cancer cells through specific downstream cytokine and integrin signals." (PMID 37143733, 2023). "In prostate cancer, HOXB13 has been proved as overexpressed in prostate cancer, and showed a higher degree of overexpression in CRPC tissues relative to prostate adenocarcinoma tissues." (PMID 36609444, 2023). "Dual carriers of HOXB13 rs138213197 T and CIP2A rs2278911 T, both of which are prostate cancer susceptibility variants, show the risk of prostate cancer with threefold higher odds than the HOXB13 T allele alone." (PMID 37097392, 2023). "HOXB13 is upregulated in breast cancer but exerts a cytostatic effect by negatively regulating the expression of TCF-4 in prostate cancer." (PMID 38203393, 2023). "Incidentally, the putative role of HOXB13 as a tumor suppressor gene has been reported in other cancers, including colorectal, gastric, kidney, melanoma, and prostate cancer." (PMID 37627895, 2023). "We, therefore, looked more precisely at the HOXB13 interactome involved in prostate cancer and found several interesting candidates known to display the same pro-oncogenic activity." (PMID 36611993, 2023). "This suggests that the possible interaction of HOXB13 and CIP2A is related to prostate cancer susceptibility." (PMID 37097392, 2023). "Some studies have confirmed that mutation in the HOXB13 gene was associated with early-onset prostate cancer men, cases with significantly elevated PSA and family history of prostate cancer." (PMID 34983599, 2022). "A more comprehensive review of studies that have investigated the oncogenic potential of HOXB13 in prostate cancer is offered elsewhere." (PMID 36212399, 2022). "In prostate cancer cells, HOXB13 interacts with the androgen receptor (AR) to modulate its transcriptional output." (PMID 35104804, 2022). "How these results fit with the observation that HOXB13 appears downregulated in mCRPC, compared to primary prostate cancer, remains to be determined." (PMID 36212399, 2022). "In the present work, we elucidated a novel mechanism for the promotion of prostate cancer bone metastasis, whereby HOXB13 transcriptionally activates and cooperates with HOXA11-AS, another putative binding partner of HOXB13." (PMID 33514011, 2021). "The most common mutations involved in prostate cancer include BRCA1/2; ATM (odds ratio (OR) = 2.18), HoxB13 (OR = 3.23), genes involved in repairing mismatched genes and genes associated with Lynch Syndrome (OR = 4.87), and CHEK2 (OR = 1.98)." (PMID 33937056, 2021). "Strongest risk effects within the hereditary prostate cancer case subset of the NFPCS were observed for rs559612720 (P = 0.0096, OR = 16.2) and rs138213197 (HOXB13 G84E, P = 0.0025, OR = 10.8)." (PMID 34059701, 2021). "In prostate cancers, HOXB13 downregulated TCF4 and its responsive genes c-Myc and cyclin D1, subsequently inhibiting cell growth." (PMID 33479226, 2021). "HOXB13 can also resist tamoxifen-induced apoptosis of cancer cells and can inhibit the growth of prostate cancer cells through the Wnt signal pathway and androgen receptor signal pathway." (PMID 34306077, 2021).
prostate carcinoma (continued). "Eleven genes previously associated with increased risk of prostate cancer (including ATM, BRCA2, and HOXB13) were identified along with ten new candidate genes." (PMID 33804961, 2021). "Our integrative analysis of these data reveals known prostate cancer specific driver genes, such as AR and HOXB13, as well as a number of top hits that are poorly characterized." (PMID 34326322, 2021). "Our results suggest that the lncRNA, HOXA11-AS, together with its transcription factor, HOXB13, regulate the osteotropism of prostate cancer cells through specific downstream cytokine and integrin signals." (PMID 33514011, 2021). "In this study, the expression of IBSP, a gene highly expressed in castration-resistant prostate cancer clinical specimens specifically metastasizing to bone, was found to be positively regulated by HOXB13/HOXA11-AS." (PMID 33514011, 2021). "Among 16 different types of cancer, HOXB13 was highly expressed in prostate cancer, suggesting its importance in prostate cancer progression." (PMID 33514011, 2021). "Although HOXB13 overexpression promotes prostate cancer metastasis by downregulating intracellular zinc and upregulating NF-kappaB signaling pathways, HOXB13 consumption promotes proliferation of PC-3 and LNCaP cells by controlling G1/S and G2/M checkpoints." (PMID 34722321, 2021). "This integrative functional genomics and clinical genomics filtering strategy revealed known prostate cancer-specific driver genes, AR and HOXB13, as the top two hits." (PMID 34326322, 2021). "We identified HOXB13 as an upstream regulator of HOXA11-AS, and found that HOXA11-AS regulated the CCL2/CCR2 signaling associated with prostate cancer bone metastasis." (PMID 33514011, 2021). "In prostate cancer, HOXB13, which is highly expressed in adulthood in the normal prostate, functions as a coregulator of AR, together with FOXA1, to modulate the epigenetic status required for prostate tumorigenesis." (PMID 33514011, 2021). "In prostate cancer, HOXB13 regulates the prostate-derived ETS family members and also facilitates cell invasion." (PMID 34722321, 2021). "In recent years, we have also begun to understand the role of HOXB13 in prostate cancer progression." (PMID 32546843, 2020). "Next, MEIS proteins were extracted from the prostate cancer cells and were found to interact with another protein called HOXB13, which regulates the activity of numerous genes." (PMID 32553107, 2020). "We thus sought to confirm a nuclear interaction between MEIS1 and HOXB13 within normal PrECs when both proteins are present and in prostate cancer cells when MEIS1 expression is increased." (PMID 32553107, 2020). "As for ERG, it synergistically regulates by physically interacting with prostate-cancer-specific regulators AR, HOXB13, and FOXA1." (PMID 33299103, 2020). "In prostate cancer, HOXB13 co-localizes with AR and acts as a repressor of AR target genes to modulate AR hormonal responses." (PMID 32546843, 2020). "We found that there is a striking correlation between the strength of the HOXC4 or HOXC6 binding sites and the strength of the binding sites for the key prostate cancer transcription factors HOXB13, FOXA1, and AR." (PMID 32012197, 2020). "(B) Western blot analysis of endogenous MEIS1, MEIS2, and HOXB13 expression from common prostate cancer cell lines and primary Prostate Epithelial Cell (PrEC) culture." (PMID 32553107, 2020). "For example, HOXB13 was identified in expression array studies as a gene highly upregulated in prostate cancer but its central importance to cancer development was not established until the analyses of cancer families were performed." (PMID 32708551, 2020). "Although it has been reported that HOXB13 suppresses the cell cycle in some human prostate cancer cells in response to its increased expression, overexpression of HOXB13 has not been reported to cause cell death, unlike in the present study." (PMID 32998228, 2020).
prostate carcinoma (continued). "Nonetheless, three proteins, AR, FOXA1, and HOXB13, are also known to mediate prostate cancer progression, and their enrichment corresponded with u2j." (PMID 33322492, 2020). "In contrast, others have linked HOXB13 expression to androgen-dependent proliferation and migration in prostate cancer cells and it has been proposed that HOXB13 contributes to the development of prostate cancer by reprogramming AR binding sites." (PMID 32012197, 2020). "In this study, we investigated clinicopathologic characteristics of HoxB13 expression in prostate cancer and compared clinicopathologic profiles of DAC and AAC of prostate." (PMID 31882852, 2019). "More importantly, the simultaneous presence of HOXB13 (G84E) and the common CIP2A (R229Q) variant confers higher prostate cancer risk and disease aggressiveness, as well as poor prognosis." (PMID 31013831, 2019). "In the colon cfDNA pool, TFs EVX2, DLX2, HNF1A, HNF4A, and HNF4G and TFs AR and HOXB13 in the prostate cancer cfDNA pool had increased accessibilities, whereas FOXA1 exceeded the >5 z-score threshold in both the prostate and breast pool." (PMID 31604930, 2019). "Collectively, our results indicate that metastasis of prostate cancers is a highly orchestrated event regulated by the transcriptional of activity of the homeobox gene HOXB13." (PMID 31273254, 2019). "HOXB13 has been reported to function as a growth promoter and growth suppressor in prostate cancer models, depending on factors such as tumour androgen sensitivity status and cellular localisation of the protein (reviewed in17)." (PMID 29259341, 2017). "We propose that the acquisition of AR binding at the enhancer, which triggers a decline in GR expression, is likely a consequence of the reprogrammed AR cistrome in prostate cancer versus normal tissue, which is enriched at HOXB13 and FOXA1 sites." (PMID 28891793, 2017). "HOXB13, for instance, has a controversial role in prostate cancer development because it has been suggested to act both as an oncogene and as a tumor-suppressor gene." (PMID 28808656, 2017). "Still, the cohort size is large enough to confirm the known expression rates of the markers under question and it is the first study to critically analyze HOXB13 in direct comparison to these other markers in prostate cancer metastases." (PMID 28555048, 2017). "We identified 101 heterozygous carriers of G84E who underwent radical prostatectomy for prostate cancer between 1985 and 2011 and matched these men by race, age and tumor grade to 99 HOXB13 wild-type controls." (PMID 28186998, 2017). "Despite this controversy, it was demonstrated that hormone-refractory tumors overexpress HOXB13 when compared to androgen-dependent carcinomas and its overexpression has been shown to promote prostate cancer invasion and metastasis." (PMID 28050579, 2016). "SFMBT2 interacts with YY1 and regulates cell growth through repression of the HOXB13 gene in DU145 prostate cancer cells." (PMID 27340776, 2016). "The mammalian PcG protein SFMBT2 has been shown to play an important role in prostate cancer cell growth through HOXB13 gene regulation via interaction with YY1." (PMID 27340776, 2016). "Several studies have further used immunohistochemistry to show that HOXB13 is often expressed at high levels in prostate cancer." (PMID 25825985, 2015). "The results of our study identify HOXB13 overexpression as a strong prognostic factor in prostate cancer, and suggest clinically relevant in-vivo interactions with its binding partner androgen receptor." (PMID 25825985, 2015). "The data also demonstrate, that prostate cancers generally show increased HOXB13 expression levels as compared to normal prostate epithelium." (PMID 25825985, 2015).
prostate carcinoma (continued). "With this reference panel, they imputed the HOXB13 G84E into 14,940 prostate cancer cases and 16,546 controls that were typed on the iCOGS array; however, they reported inadequate imputation quality." (PMID 25629170, 2015). "AR ChIP-seq differential binding analysis yielded HOXB13 motif as selectively enriched in resistant tissue, suggesting a role of HOXB13 in resistant prostate cancer as found by others." (PMID 26412853, 2015). "Data from two other studies using a more sensitive IHC protocol had earlier demonstrated that at least some HOXB13 expression can occur in every prostate cancer." (PMID 25825985, 2015). "In summary, our study highlights HOXB13 as strong and independent prognostic marker in prostate cancer, and a promising candidate for a routine clinical application." (PMID 25825985, 2015). "We analyzed the prognostic impact of HOXB13 expression by immunohistochemistry on a tissue microarray containing more than 12,400 prostate cancers." (PMID 25825985, 2015). "HOXB13 promotes or represses prostate cancer cell proliferation depending on the cellular context, such as with androgen receptor expression." (PMID 25944620, 2015). "Our notion, that HOXB13 is highly relevant for the biology of prostate cancer is further substantiated by the strong link of high expression with unfavorable tumor phenotype and poor outcome in this study." (PMID 25825985, 2015). "YY1 also participates in the repression of HOXB13 expression in prostate cancer cells through an epigenetic mechanism involving histone acetylation modification." (PMID 24705708, 2014). "HOXB13 gene is silenced in AR− prostate cancer cells and overexpression of HOXB13 in AR− prostate cancer cells resulted in significant inhibition of cell growth." (PMID 22808286, 2012). "Our results revealed that ATRA inhibited the growth of DU145 prostate cancer cells through upregulating HOXB13 expression by reducing its methylation level." (PMID 22808286, 2012). "Overexpression of HOXB13 in AR− prostate cancer cells resulted in significant inhibition of cell growth." (PMID 22808286, 2012). "Overexpression of HOXB13 in AR− prostate cancer cells can also result in significant inhibition of cell growth." (PMID 22808286, 2012). "Results from this study implicated a novel effect of ATRA in inhibition of the growth of AR− resistant human prostate cancer cells through alteration of HOXB13 expression as a result of epigenetic modifications." (PMID 22808286, 2012). "It therefore becomes important to understand the function of DNMT3b in silencing of HOXB13 gene in DU145 prostate cancer cells." (PMID 22808286, 2012). "We then investigated the molecular events that are involved in HOXB13 gene silencing in AR− prostate cancer cells." (PMID 22808286, 2012). "Specifically, ATRA inhibits the proliferation of DU145 prostate cancer cells through reducing the methylation level of HOXB13 promoter induced by EZH2 and DNMT3b." (PMID 22808286, 2012). "We discovered that ATRA was able to induce the growth arrest and to increase HOXB13 expression in AR− prostate cancer cells." (PMID 22808286, 2012). "Nevertheless, data presented in this report provide evidence that ATRA treatment inhibited the growth of DU145 prostate cancer cells, through a mechanism that involved the upregulation of HOXB13 by reducing the methylation level at gene’s promoter." (PMID 22808286, 2012). "We have previously demonstrated that the HOXB13 homeodomain protein functions as a prostate cancer cell growth suppressor by inhibiting androgen-mediated signals." (PMID 20504375, 2010). "Functionally, in an androgen-free environment minimal induction of HOXB13 in LNCaP prostate cancer cells, to the level of the normal prostate, markedly promoted cell proliferation while suppression inhibited cell proliferation." (PMID 20504375, 2010).
prostate carcinoma (continued). "Real-time RT-PCR revealed GADD45A, MX1, EPB41L3/DAL1, and FBLN1 as generally downregulated in prostate cancer, whereas HOXB13 and EPB41L4B were upregulated." (PMID 17280610, 2007). "Recent studies in which overexpression of HOXB13 was forced in prostate cancer PC3 cells did, however, indicate that this homeodomain protein has the potential to act as a suppressor of cell growth possibly through modulating the expression of TCF-4." (PMID 15583692, 2005). "In prostate cancers, HOXB13 negatively regulates β-catenin/TCF4-mediated transactivation and subsequently inhibits cell growth." (PMID 15928669, 2005). "Recently, we demonstrated that the forced expression of HOXB13 suppressed the growth of metastatic prostate cancer cells by disrupting β-catenin/TCF signals." (PMID 15928669, 2005). "Previously, we have observed that HOXB13 negatively regulates the expression of TCF4 in prostate cancer cells." (PMID 15928669, 2005). "Quantitative RT–PCR demonstrated the specificity of expression of HOXB13 in prostate tissue and revealed its ubiquitous expression in a series of 37 primary prostate cancers and 20 normal prostates." (PMID 15583692, 2005). "Depending on the status of AR, suppression of either pathway by HOXB13 seems to inhibit the growth of prostate cancer cells." (PMID 15928669, 2005). "In addition to TERT, we found rare non-synonymous variants in three genes associated with decreased prostate cancer risk (ANO7, SPDL1 and AR), and three genes associated with increased risk (HOXB13, CHEK2 and BIK)." (PMID 39971927, 2025). "In addition, strong nuclear HOXB13 expression has been detected in certain types of tumors including prostate carcinoma and cauda equina neuroendocrine tumor (previously paraganglioma)." (PMID 40137996, 2025). "For this, weused the PC-3 prostate cancer line, which shows a high levelof HOXB13 gene expression." (PMID 41164275, 2025). "Dysregulation of HOXB13 promotes prostate cancer (PCa) through diverse mechanisms." (PMID 41277556, 2025). "HOXB13 is upregulated in breast cancer, whereas its expression is suppressed in prostate cancer." (PMID 39329491, 2024). "Finally, we revealed a novel interaction that was important for HOXB13 proliferative activities in a prostate-cancer-derived cell line." (PMID 36611993, 2023). "Also of interest were several genes associated with prostate cancer metastases including FOXA1, EZH2, SCHLAP1, CDH1, SOX4, SOX9, HOXB13, and TGFBR3." (PMID 38067373, 2023). "ALAN identified direct protein-protein interactions in prostate cancer (AR, HOXB13, and FOXA1)." (PMID 37059746, 2023). "Altogether, these results showed that CREB3L4 could work as the collaborative partner of HOXB13, potentially through direct protein–protein interactions, to promote its proliferative activity in prostate-cancer-derived PC-3 cells." (PMID 36611993, 2023). "Thus, HOXB13 is the target gene of SLC12A5/YTHDC1 complex in the nucleus that mediates the pro-tumor function of SLC12A5 in prostate cancer." (PMID 36609444, 2023). "Our data reveal SLC12A5 could bind with YTHDC1 to form a SLC12A5-YTHDC1 complex to regulate prostate cancer specific transcription factor HOXB13 in an m6A-dependent manner, uncovering a novel mechanism about how SLC12A5 promotes tumor progression." (PMID 36609444, 2023). "Interestingly, SLC12A5 was detected in the cell nucleus and formed a complex with nuclear m6A reader YTHDC1, which in turn upregulated HOXB13 to promote the prostate cancer progression." (PMID 36609444, 2023). "For example, the G84E mutation in HOXB13 is thought to promote prostate cancer initiation, but not progression and metastasis." (PMID 35080776, 2022). "Conversely, tumour‐suppressor functions of HOXB13 in prostate cancer seem to depend on its ability to block cell division through the downregulation of cyclin D1 through competition for TCF4 binding to its promoter, and androgen signalling through direct interaction with the androgen receptor." (PMID 35080776, 2022).